FA2H (fatty acid 2-hydroxylase)
Diseases named in the same sentence as FA2H in open-access papers (continued):
Sharing a sentence is not in itself a finding about the gene and the disease.
ichthyosis (1 paper, 2021). Disorders of cornification that are characterized by visible scaling and/or hyperkeratosis of most or all of the skin. "This variant is therefore the first in any domestic animal species to be associated with IC, and FA2H should be considered an additional candidate gene for syndromic forms of ichthyosis in humans." (PMID 34599683, 2021). "In conclusion, this study represents the first report of an FA2H-related autosomal recessive inherited skin disorder in a mammalian species and adds FA2H to the list of candidate genes for ichthyosis in humans and animals." (PMID 34599683, 2021). "However, to the best of our knowledge, no pathogenic variant in the FA2H associated to a form of ichthyosis has been reported in both animal and human species." (PMID 34599683, 2021).
impaired glucose tolerant (1 paper, 2024). "Interestingly, the expression of FA2H is significantly lower in impaired glucose tolerant (IGT) and T2D islets when the insulin secretion index is significantly suppressed than in non-diabetic islets, indicating potential involvement of FA2H in human β cell functions." (PMID 39442620, 2024).
insulinoma (1 paper, 2024). "We examined FA2H expression in the glucose-responsive insulinoma MIN6 cells by immunofluorescence staining and observed strong immunoreactivity." (PMID 39442620, 2024).
lentivirus infection (1 paper, 2024). Virus diseases caused by the Lentivirus genus. "To explore the role of FA2H in β cell insulin secretion, we generated FA2H knockout (FA2H KO) MIN6 cells by CRISPR/Cas9 and FA2H overexpression (FA2H OE) cells by lentivirus infection." (PMID 39442620, 2024).
liver cancer (1 paper, 2021). An epithelial or non-epithelial malignant neoplasm that arises from the liver. "A-Raf and fatty acid 2-hydroxylase (FA2H) are expressed in the early stage of liver cancer, both during progression and in tumor stage." (PMID 34651050, 2021).
mast syndrome (1 paper, 2015). "Such conditions include HSP with thin corpus callosum (SPG11/15 mutations), SPG35/FA2H-associated HSP, Troyer syndrome (SPG20) and Mast syndrome (SPG21), SPG26/B4GALNT1, SPG30/KIF1A, SPG39/PNPLA6 and SPG46/GBA2." (PMID 25480570, 2015).
pantothenate kinase-associated neurodegeneration (1 paper, 2013). "In addition to the core syndromes of pantothenate kinase-associated neurodegeneration (PKAN, NBIA1) and PLA2G6-associated neurodegeneration (PLAN, NBIA2), several other genetic causes have been identified (including FA2H, C19orf12, ATP13A2, CP and FTL)." (PMID 23814539, 2013).
schwannoma (1 paper, 2021). A benign, usually encapsulated slow growing tumor composed of Schwann cells. "Particularly, a study demonstrated that absence of FA2H lead to the impairment of cAMP-dependent cell cycle exit of Schwannoma cells, suggesting that FA2H sphingolipids may negatively regulate the cell cycle." (PMID 34599683, 2021).
temporal lobe epilepsy (1 paper, 2021). A localization-related (focal) form of epilepsy characterized by recurrent seizures that arise from foci within the temporal lobe, most commonly from its mesial aspect. "Similar to this study, increased expression of MOG, PLP1, ABCA2, FA2H, TF, ASPA was demonstrated in high-spiking regions of cortical areas of temporal lobe epilepsy patients." (PMID 34301297, 2021).
cancer (14 papers, 2013 to 2025). A tumor composed of atypical neoplastic, often pleomorphic cells that invade other tissues. "Additionally, down-regulation or up-regulation of FA2H has been associated with different types of cancer." (PMID 36846236, 2023). "The observation that FA2H expression level affects tumor progression in different cancer types further strengthened interest in the FA2H gene and 2hFA-SL." (PMID 36902339, 2023). "This positions FA2H as a potential biomarker and therapeutic target in ovarian and other cancers." (PMID 40510341, 2025). "Some studies have shown that over-expression of FA2H may be related to a protective effect against cancer via stimulation of anti-cancer cellular mechanisms." (PMID 36846236, 2023). "Several micro-RNAs target the human FA2H gene and may play important roles in its regulation in cancer or other diseases that have been identified." (PMID 36902339, 2023). "A low expression level of FA2H correlates with a poor prognosis in many cancers." (PMID 36902339, 2023). "For this, we analyzed IL6 expression and cancer cell stemness under FA2H down- and up-regulation." (PMID 31709178, 2019). "Evidences at both transcriptional and translational levels as well as functional studies using established stable cells with FA2H modulation suggested the tumor suppressive roles of FA2H on cancer stemness and cell migration via inhibiting the STAT3/IL6 axis and NFkB mediated signaling." (PMID 31709178, 2019). "FA2H may affect cisplatin sensitivity by modifying lipid metabolism and cell survival signaling, underscoring the need for further investigation into its dual roles in lipid metabolism and cancer progression." (PMID 40510341, 2025). "In addition, upregulation of FA2H in malignant tumors has been reported which may lead to cancer specific cytotoxic effects of elisidepsin." (PMID 24317474, 2013). "A different picture emerged in more recent studies, which examined FA2H expression but not 2hFA-SL levels in various cancer types." (PMID 36902339, 2023). "Among the three pathways that canonically control cancer cell stemness, migration and proliferation, we found that FA2H did not alter the total phosphorylation but the nuclear phosphorylation level of JNK." (PMID 31709178, 2019).
tumor (14 papers, 2013 to 2025). "It is possible that when PTEN, which encodes an important tumor suppressor, is completely lost, other genes with tumor suppressive roles such as FA2H are activated as alternative signalings to prevent cells from running chaotic." (PMID 31709178, 2019). "The over-expression of FA2H in tumor cell lines decreased cell proliferation, induced apoptosis and inhibited the epithelial–mesenchymal transition-associated gene expression." (PMID 36902339, 2023). "The effects of (R)-2-OHPA treatment alone in tumor suppression in vivo were minimal, while FA2H knockdown significantly enhanced tumor growth." (PMID 33344772, 2020). "Previous research indicated that FA2H can affect the cell cycle and cell migration and promote the sensitivity of tumor cells to drugs and regulate the drug resistance of tumor cells." (PMID 33344772, 2020). "After transcriptional and translational in vitro validations, FA2H was revealed having potential tumor suppressive roles, which is likely under-expressed in triple negative breast tumors (p = 0.0453)." (PMID 31709178, 2019). "As FA2H, the enzyme thought to be responsible for the generation of the target of elisidepsin, is oxygen dependent and tumor hypoxia is widespread in advanced tumors, we have decided to investigate its role in the mechanism of action of elisidepsin." (PMID 24317474, 2013). "Moreover, FA2H partially inhibits tumor growth by impacting GLUT1 level and glucose sensing by AMPK." (PMID 39442620, 2024). "It is therefore unclear whether the anti-tumor and pro-apoptotic pathways activated by 2OHOA treatment and FA2H overexpression are related." (PMID 36902339, 2023). "Additionally, we noticed deep deletions of the TRIM29 and FA2H genes in the TCGA cohort, which is consistent with their reported tumor-suppressive roles in BC." (PMID 37370814, 2023). "sensitivity to the drug PM02734 is significantly enhanced in tumor cells that over-express FA2H." (PMID 36902339, 2023). "This or these currently unknown enzyme(s) and FA2H and their reaction products may, in part, fulfill opposing roles, as suggested by the analysis of tumor cells." (PMID 36902339, 2023). "Taken together, we propose the tumor suppressive roles of FA2H on TNBC control and the driving mechanism, which may potentially be used in the therapeutic design against TNBCs." (PMID 31709178, 2019). "However, tumor hypoxia is known to decrease the rate of hydroxylation due to shortage of oxygen, which acts against the tumor-specificity of elisidepsin by reducing the activity of FA2H." (PMID 24317474, 2013). "Since metabolic enzymes display noncanonical functions in tumour initiation and progression, we asked if the pro-metastasis function of FA2H was dependent on its enzyme activity." (PMID 36274060, 2022).
neurodegenerative disease (6 papers, 2011 to 2025). A disorder of the central nervous system characterized by gradual and progressive loss of neural tissue and neurologic function. "Mutated FA2H has been associated with neurodegenerative diseases." (PMID 21599921, 2011).
nervous system diseases (3 papers, 2020 to 2025). "αOHCer serve as precursors for the αOH glycosphingolipids required for myelin sheath maintenance and mutations in FA2H have been identified in patients with neurological disease and correlate with clinical signs of demyelination." (PMID 40386785, 2025). "Loss-of-function mutations in fatty acid-2-hydroxylase (FA2H) are responsible for the complex form of autosomal recessive HSP (SPG35) and allelic neurological disorders." (PMID 32180696, 2020). "The FA2H gene in mammals is involved in drug resistance and is related to nervous system diseases." (PMID 38197633, 2024).
FA2H also shares sentences with these, for which no sentence is quoted: Spastic paraparesis (3 papers); Cerebellar atrophy (2); colorectal cancer (2); epilepsy (2); hereditary spastic paraplegia 35 (2); infection (2); Kufor-Rakeb syndrome (2); lysosomal disorder (2); neuroferritinopathy (2); neuropathy (2); optic atrophy (2); schizophrenia (2); spastic ataxia (2); adenocarcinoma (1); asthma (1); autism (1); autism spectrum disorder (1); axonal motor neuropathy (1); bacterial infection (1); brain disease (1); cardiovascular diseases (1); cataract (1); cognitive decline (1); colon cancer (1); esophageal squamous cell carcinoma (1); fatty liver disease (1); Huntington disease (1); Hydrocephalus (1); ichthyosis congenita (1); Insulin resistance (1).
A further 19 diseases each share a sentence with FA2H in 1 paper.